PTPN11 (protein tyrosine phosphatase non-receptor type 11)
Diseases named in the same sentence as PTPN11 in open-access papers (continued):
Sharing a sentence is not in itself a finding about the gene and the disease.
cancer (continued). "Finally, we were surprised that the E3 testis clusters formed by different PTPN11 variants have very similar anatomical distributions, average testis variant frequencies and MaxPFs regardless of their NS1 case recurrence rate or contribution to sporadic cancers in the general population." (PMID 36349709, 2022). "In oral squamous cell carcinoma, miR-186 directly binds to 3’ UTR of PTPN11 mRNA and inhibits the expression, which suppresses the signaling activity of Erk and AKT that is required for cancer cell growth." (PMID 35957898, 2022). "In this research, we examined the relationship between PTPN11 expression and TMB and MSI in all TCGA cancers." (PMID 35802774, 2022). "We observed novel recurring amino acid changes in the cancer-related genes ZEB2 H1038R (n = 3) and PTPN11 S502L (n = 2)." (PMID 30862934, 2019). "Tyrosine-protein phosphatase non-receptor type 11 (PTPN11; also known as PTP-1D, PTP-2C, or SHP2) is a PTP activated mainly by RTKs and is one of the representative PTPs that have oncogenic roles in various cancers." (PMID 30791455, 2019). "These four pathways were proteoglycans in cancer (ANK2, FASLG, HSPG2, PTPN11, STAT3, and VEGFA), HIF-1 signaling (ARNT, STAT3, and VEGFA), FoxO signaling (FASLG, SMAD4, and STAT3), and ECM-receptor interaction (HSPG2 and LAMA2)." (PMID 29300322, 2018). "However, the methylation level of the PTPN11 gene exhibited notable discrepancies between THCA cancer and control samples (FDR ≤ 0.05), and methylation was significantly negatively correlated with PTPN11 gene expression (cor < −0.3, FDR ≤ 0.05)." (PMID 41367010, 2025). "Allosteric inhibitors of wild-type PTPN11 that hold the phosphatase in the auto-inhibited confirmation and therefore limit signaling through the RAS/MAPK pathway are currently in clinical trials for cancer." (PMID 35178568, 2022). "As of yet, neither the expression profile of PTPN11 nor its significance in pan-cancer diagnosis has been clarified." (PMID 35802774, 2022). "Activating mutation of SHP-2, encoded by the protein tyrosine phosphatase nonreceptor type 11 (PTPN11) gene, has been observed in various cancers." (PMID 36380016, 2022). "However, it is increasingly apparent that phosphatases themselves can propagate signals in response to growth factors; with the best example being PTPN11/SHP2; a key therapeutic target in cancer." (PMID 30924770, 2019). "Moreover, the inhibitory effects of anti-miR-500a-3p on cancer stem cell phenotypes and activity of STAT3 signaling were reversed by silencing SOCS2, SOCS4 and PTPN11 in miR-500a-3p-downexpressing cells, respectively." (PMID 28750679, 2017). "In addition, PIK3CA.E542K, PTPN11.G268S, AKT1E17K and APC.T1556Nfs*3 were also observed in multiple cancer types." (PMID 29038591, 2017). "Interestingly, PTPN11 and PTPRJ share around 24 gene interactions, which enriched important pathways in cancer such as ERBB signalling pathway, cytokine-cytokine interactions pathway, JAK/STAT signalling pathway and others." (PMID 24885312, 2014). "At the pan-cancer level, various mutations, including those in FLG, CUBN, and PPFIA2, significantly increased Y62 phosphorylation of PTPN11; however, none of these mutations elevated Y62 phosphorylation of PTPN11 to an outlier level (right)." (PMID 41540913, 2026). "However, miR-500a-3p promotes HCC cancer stem cell properties by targeting PTPN11, a negative regulator of the JAK/STAT3 signaling pathway." (PMID 35957898, 2022). "Additionally, we applied the GTEx dataset to further corroborate the expression profiles of PTPN11 in several other cancers, that lacked healthy tissues matched in TIMER2 dataset." (PMID 35802774, 2022). "Of the 186 patients without germline P/LP variants and available cancer genomes–exomes, 41/186 patients had a somatic variant in the DNA damage response pathway (ATRX, ATM, PPM1D, POLE) and 21/186 had a variant in the MAPK-ERK pathway (BRAF, NF1, PTPN11, MAPK12)." (PMID 40072012, 2025).
cancer (continued). "However, a thorough pan-cancer analysis of PTPN11 is still lacking." (PMID 35802774, 2022). "Down-regulation of LINC00673 may attenuate the interaction of PTPN11 with an E3 ubiquitin ligase PRPF19 and suppress the ubiquitin-mediated PTPN11 degradation; these processes enhance an oncogenic signaling whereas diminish STAT1-dependent anti-oncogenic signaling in cancer cells." (PMID 32523949, 2020). "Our findings further reveal miR-500a-3p promotes the cancer stem cell characteristics via targeting multiple negative regulators of JAK/STAT3 signaling pathway, including SOCS2, SOCS4 and PTPN11, leading to constitutive activation of STAT3 signaling." (PMID 28750679, 2017). "Indeed, multiple upstream regulators of Ras activation such as SOS1, SOS2, PTPN11, and GAB1 exhibit significant negative correlations with NF1 in the Cancer Dependency Map, supporting the importance of these genes as functionally opposing NF1 function." (PMID 40587782, 2025).
hematologic malignancies (27 papers, 2011 to 2026). "Especially, mutations in PTPN11 have been reported in malignant hematological diseases and solid tumors." (PMID 37265961, 2023). "Other recent studies provide additional new insights into the mechanisms by which PTPN11 mutations induce hematologic malignancies." (PMID 21799948, 2011). "Activating mutations in the PTPN11 gene may trigger signaling pathways leading to the development of hematological malignancies, but are rarely found in solid tumors." (PMID 38504984, 2024). "Further understanding SHP-2 signaling activities and identification of its interacting proteins/substrates will shed light on the pathogenesis of PTPN11-associated hematologic malignancies, which, in turn, may lead to novel therapeutics for these diseases." (PMID 21799948, 2011). "Remarkably, mutations in PTPN11 have been identified in several human diseases, such as the developmental disorders Noonan syndrome (NS) and Leopard syndrome (LS), childhood hematologic malignancies, and sporadic solid tumors." (PMID 21799948, 2011). "Quite frequently, hematological malignancies and Noonan/LEOPARD syndrome display PTPN11 gene mutations." (PMID 38504984, 2024). "NGS covering 51 genes related to hematological malignancies revealed NRAS-p.Gly12Asp, PTPN11-p.Asp61Val, PTPN11-p.Thr468Met, KRAS-p.Gly12Val, and CALR-p.Gly108Arg mutations." (PMID 35912172, 2022). "This notion is further supported by the fact that both NS and LS are associated with increased risk of hematologic malignancies although PTPN11 mutations found in NS and LS activate and inactivate SHP-2 enzymatic activity, respectively." (PMID 21799948, 2011).
infection (26 papers, 2011 to 2025). The state of being infected such as from the introduction of a foreign agent such as serum, vaccine, antigenic substance or organism. "Five children (9%) with PTPN11 gene mutation developed late onset feeding problems, 2 after an intercurrent infection, 2 children post-operatively and 1 due to behaviour problems." (PMID 32394265, 2020). "In contrast, genes such as Abce1 and Ptpn11 were only upregulated following rpoB-H445Y Mtb infection, whereas Uba7 was upregulated only during wt Mtb infection." (PMID 38603763, 2024). "The results showed that circRNA hsa_circ_0065336 and target gene PTPN11 were both up-regulated after infection with T. asahii, whereas miRNA miR-505-3p was down-regulated." (PMID 34983376, 2022). "We first measured the expression levels of hsa_circ_0065336, miR-505-3p and PTPN11 in THP-1 cells after infection with T. asahii at time points of 0, 3, 6, 9, and 12 h." (PMID 33750466, 2021). "Ptpn11 is the gene that encodes for SHP-2 and it was crucial for the induction of interleukin 1b (IL-1b), IL-6 and IL-23 and responses of the Th17 subset of helper T cells in controlling infection." (PMID 34759909, 2021). "Analysis of luciferase reporter expression in the absence of GPC-N114 at 6 h postinfection (i.e., within a single replication cycle) showed that knockout of ADAM9 and PTPN11, but not FGFR1, significantly inhibited EMCV infection." (PMID 31409686, 2019).
genetic disorder (15 papers, 2012 to 2024). "PTPN11 germline mutations are associated with genetic diseases." (PMID 36140242, 2022).
adenocarcinoma (8 papers, 2010 to 2024). A common cancer characterized by the presence of malignant glandular cells. "For the patient with PAF and adenocarcinoma in the same lobe, SNVs of HER2 were detected in adenocarcinoma, and SNVs of JAK1 and PTPN11 genes were found in PAF, suggesting that PAF is unlikely to be related to the occurrence of adenocarcinoma." (PMID 34350112, 2021).
cardiovascular disease (6 papers, 2010 to 2025). "Patients with PTPN11-associated NS are distinguishable from patients with RAF1 variants, and they have a dissimilar risk for cardiovascular disease, with PTPN11 presenting a higher risk for PVS and less risk for HCM." (PMID 39202376, 2024).
autosomal dominant disease (4 papers, 2014 to 2021). Autosomal dominant form of disease. "LEOPARD (OMIM #151,100), also known as neuro-cardio-cutaneous (NCFC) syndrome, is a rare autosomal dominant disease that is characterized by multisystemic disorders and typical germline PTPN11 mutations." (PMID 34488904, 2021).
blood cancer (3 papers, 2022 to 2023). "Further, it was demonstrated that PTPN11 is necessary for BCR::ABL1-induced hematologic neoplasms, as its deletion compromised induction of CML in mice." (PMID 37384296, 2023).
CNS tumors (3 papers, 2024 to 2026). "Ten patients with CNS tumors, including 7/17 (41%) with PTPN11 variants, required chemotherapy." (PMID 41784910, 2026). "Therefore, attention should be focused on investigating CNS tumors in patients with NS bearing a PTPN11 mutation." (PMID 39336782, 2024).
hematologic cancers (2 papers, 2018 to 2022). "Activating mutations in PTPN11, encoding the cytosolic protein tyrosine phosphatase SHP2, result in developmental disorders and act as oncogenic drivers in patients with hematologic cancers." (PMID 30375388, 2018).
PTPN11 also shares sentences with these, for which no sentence is quoted: prostate carcinoma (18 papers); triple-negative breast carcinoma (18); osteoporosis (12); autoimmune disease (10); Sepsis (10); cardiofaciocutaneous syndrome (8); multiple myeloma (8); esophageal squamous cell carcinoma (7); neurofibromatosis type 1 (7); cholangiocarcinoma (6); metabolic disease (6); CHARGE syndrome (5); glaucoma (5); Infertility (5); metastatic tumors (5); neurodevelopmental disorder (5); pulmonary diseases (5); ventricular septal defect (5); head and neck cancer (4); heart disease (4); inflammation (4); inflammatory bowel disease (4); lung squamous cell carcinoma (4); lymph node metastasis (4); neurofibromatosis (4); oral cancer (4); Thrombocytopenia (4); achondroplasia (3); breast (3); breast adenocarcinoma (3).
A further 328 diseases each share a sentence with PTPN11 in 3 papers or fewer.